STPG2 (sperm tail PG-rich repeat containing 2)
Synonyms: C4orf37; MGC46496
Tractability: No criterion of Open Targets' tractability assessment is met for any kind of drug.
Gene: Protein-coding gene on chromosome 4 (97,184,093 to 98,143,476, reverse strand). Ensembl gene ENSG00000163116.
Subcellular location (Human Protein Atlas): Principal piece
Genetic constraint (gnomAD): Loss-of-function variants: 27 observed, 29.06 expected, observed/expected ratio (o/e) 0.93, 90% interval 0.68 to 1.28. The upper end of that interval is the gene's LOEUF score, 1.28, which puts it in group 5 of 6, group 1 being the genes least tolerant of losing a copy. Missense variants: 468 observed, 417.27 expected, observed/expected ratio (o/e) 1.12, 90% interval 1.04 to 1.21. Synonymous variants: 164 observed, 145.19 expected, observed/expected ratio (o/e) 1.13, 90% interval 0.99 to 1.29.
Homologues: Orthologues: chimpanzee STPG2 (99% identical), macaque STPG2 (91% identical), dog STPG2 (75% identical), rabbit STPG2 (73% identical), pig STPG2 (67% identical), rat Stpg2 (61% identical), mouse Stpg2 (60% identical), tropical clawed frog STPG2 (45% identical), zebrafish stpg2 (33% identical). Paralogues in human: STPG1 (16% identical), CIMAP1B (13% identical), CIMAP1A (12% identical), CIMAP1D (11% identical), CIMAP1C (9% identical).
Diseases named in the same sentence as STPG2 in open-access papers:
STPG2 is named in the same sentence as 6 diseases in open-access papers, as found by Europe PMC text mining. Sharing a sentence is not in itself a finding about the gene and the disease. The quoted sentences say what the papers report.
angiosarcoma (1 paper, 2023). A malignant tumor arising from the endothelial cells of the blood vessels. "This event might explain why STPG2 was found to be upregulated among the most differentially expressed genes in the leiomyosarcoma case versus the angiosarcoma and intimal sarcoma cases." (PMID 36673024, 2023).
Azoospermia (1 paper, 2023). Absence of any measurable level of sperm,whereby spermatozoa cannot be observed even after centrifugation of the semen pellet. "Interestingly, in our Taiwan study, the KIF6 SNP (rs2273063) and STPG2 (rs2903150) co-occur in an 80% mutation rate in azoospermia and oligozoospermia patients with 20% MAF in ordinary men of Taiwan by Sanger sequencing." (PMID 37895049, 2023). "The SPATA16, CFTR, KIF6, STPG2, and DRC7 mutations are associated with male infertility, specifically azoospermia, and a further examination of this genetic function is required." (PMID 37895049, 2023).
infertile (1 paper, 2023). "Sanger sequencing was employed to confirm the presence of SNPs on KIF6 and STPG2, facilitating a gene comparison between infertile and fertile men." (PMID 37895049, 2023).
leiomyosarcoma (1 paper, 2023). An uncommon, aggressive malignant smooth muscle neoplasm, usually occurring in post-menopausal women. "Another noteworthy event in the leiomyosarcoma case was the fusion between the PSIP1 gene, involved in the DNA-binding transcription factor and chromatin-binding activity, and the STPG2 gene, which was validated by Sanger sequencing." (PMID 36673024, 2023).
male infertility (1 paper, 2023). The inability of the male to effect fertilization of an ovum after a specified period of unprotected intercourse. "Our experimental results have pinpointed evidence for a potential link between genetic variations in the KIF6, DRC7, and STPG2 genes with male infertility." (PMID 37895049, 2023). "In this study, an Ampiseq targeted NGS panel and Illumina TruSeq WES were both used to pinpoint six specific genes (KIF6, DRC7, STPG2, SPATA16, CFTR, CMTM2) that play a role in MT association and spermiogenesis, which are crucial factors in understanding the causes of male infertility." (PMID 37895049, 2023).
STPG2 also shares sentences with these, for which no sentence is quoted: intimal sarcoma (1 paper).